TFRC (transferrin receptor)
Diseases named in the same sentence as TFRC in open-access papers (continued):
Sharing a sentence is not in itself a finding about the gene and the disease.
Obesity (31 papers, 2013 to 2026). Accumulation of substantial excess body fat. "We next assess the association of TFRC levels with obesity in an overweight subjects (BMI ≥25 kg/m2, n = 9) and lean controls (18 kg/m2 < BMI < 24.9 kg/m2, n = 12)." (PMID 37646182, 2023). "Future studies to validate the clinical relevance of missense variant p.I337V of TFRC with obesity need to be conducted in larger cohorts." (PMID 37646182, 2023). "With genetic analysis of coding regions in TFRC gene, a rare missense variant p.I337V was identified to be enriched in obesity cases." (PMID 37646182, 2023). "Reduced TFRC levels and its rare variant p.I337V with protein instability are associated with human obesity." (PMID 37646182, 2023). "Overall, we revealed the association of TFRC with human obesity and proposed TFRC as a promising therapeutic target for obesity and metabolic diseases in human." (PMID 37646182, 2023). "Rare and low‐frequency transferrin receptor (TFRC) nonsynonymous variants identified in young Chinese with obesity and lean controls." (PMID 37646182, 2023). "In the present study, we have provided initial evidence supporting the association between TFRC levels and rare variants with human obesity." (PMID 37646182, 2023). "In the present study, we sought to unveil the association of TFRC levels and TFRC variants with human obesity." (PMID 37646182, 2023). "In this nested cohort comparison of two prospective pregnancy studies, obesity was negatively associated with maternal iron status, as evidenced by measurement of soluble transferrin receptor and the soluble transferrin receptor to serum ferritin ratio." (PMID 30061547, 2018). "We next examined whether TFRC variants/mutants exist in human and how they impact the development of human obesity." (PMID 37646182, 2023). "Overall, our study emphasized that TFRC rare variant may be associated with obesity development and TFRC gene may be a potential therapeutic target in treating human obesity." (PMID 37646182, 2023). "Besides, the rare variant p.I337V in TFRC was marginally associated with human obesity and the I337V amino acid substitution led to TFRC protein instability." (PMID 37646182, 2023). "Moreover, several studies have reported that transferrin and soluble transferrin receptor (sTfR) are associated with obesity, metabolic syndrome and other cardiovascular risk factors in adults and children." (PMID 30755213, 2019). "In addition, via whole‐exome sequencing (WES), we discovered a rare heterozygous missense variant p.I337V in TFRC, which showed a tendency to enrich in obese subjects, indicating its potential contribution to obesity possibly due to its impaired protein stability." (PMID 37646182, 2023). "However, whether TFRC levels and variants are associated with human obesity is unknown." (PMID 37646182, 2023). "Further studies are warranted to potentially target TFRC signaling and iron metabolism in obesity treatment." (PMID 37646182, 2023). "Of note, a heterozygous p.I337V substitution in TFRC tended to be enriched in severely obesity group (odds ratio, 2.30; 95% confidence interval, 0.98–5.38; p = .06)." (PMID 37646182, 2023). "Some studies suggest that the soluble transferrin receptor (sTfR) may be increased in individuals with overweight or obesity, indicating a shift toward ID." (PMID 40886951, 2025). "After adjustment for covariates, younger women taking opioids had higher odds of class III obesity (OR = 2.1, 95% CI: 1.2–3.7), high serum transferrin receptor (OR = 2.3, 95% CI: 1.2–4.30), and low percent transferrin saturation (OR = 2.6, 95% CI: 1.7–4.2) than unexposed younger women." (PMID 37111110, 2023). "In addition, TFRC levels in fat are negatively correlated with BMI of human participates and positively correlated with thermogenic marker gene UCP1 levels in human biopsies, suggesting the close correlation of TFRC levels with thermogenic adipocytes and obesity progression in human." (PMID 37646182, 2023).
Obesity (continued). "Patients under 65 years old showed a higher expression of TFRC (p = 0.002), CCL5 (p < 0.001) and IFI6 (p = 0.006), and those with obesity (BMI ≥ 30) presented higher expression of OAS1 (p = 0.008) and TGFB1 (p = 0.008)." (PMID 38731851, 2024). "Mean serum ferritin, erythrocyte protoporphyrin, and soluble transferrin receptor were higher, while those of serum iron, percent transferrin saturation, and mean cell volume (MCV) were lower in women with obesity than those with normal weight (all p < 0.016)." (PMID 37242155, 2023).
ovarian carcinoma (31 papers, 2015 to 2025). A malignant neoplasm originating from the surface ovarian epithelium. "Iron, for instance, is implicated in promoting ovarian cancer through its absorption via transferrin receptor TFRC." (PMID 39744692, 2025). "Previous studies have confirmed that decreased iron transporter protein (FPN) and increased transferrin receptor (TFR1) are associated with prognosis in ovarian cancer." (PMID 38110359, 2023). "This study also demonstrated the potential value of targeting transferrin receptor or folate receptors that are overexpressed on ovarian cancer cells for quantification of tumor burden in live mice and at necropsy." (PMID 41322193, 2025). "To further validate the role of TFRC in promoting ovarian cancer malignancy, we employed shRNA to knock down TFRC expression in ovarian cancer cells." (PMID 38740757, 2024). "IHC was performed on ovarian cancer tissue, used as a positive control to validate TFRC antibody immunoreactivity (-ir), and on five primary GIST tissues with different clinicopathological features." (PMID 36291834, 2022). "Suppression of the transferrin receptor or reduction of intracellular iron levels in breast and ovarian cancers reduces cancer cell proliferation in vitro, inhibits tumor growth in vivo, and decreases metastases." (PMID 35785195, 2022). "In our study, we decided to investigate the expression of the transferrin receptor (CD71) in ovarian cancer patients and the expression of phosphorylated H2A.X protein during DNA damage." (PMID 34205023, 2021). "For example, TFRC, known as the important participant in intracellular iron transport, induced epithelial ovarian cancer (EOC) cell proliferation and metastasis via upregulating the expression level of AXIN2." (PMID 34362387, 2021). "Our studies confirmed differences in the transferrin receptor mRNA levels between ovarian cancer tissue and benign cyst tissue." (PMID 34205023, 2021). "Transferrin (Tf) usually binds to the transferrin receptor (TfR1) to transport iron from the intracellular environment into cells in the form of iron-transferrin complexes, a process that is important in ovarian cancer, sarcoma, and other tumors were significantly up-regulated." (PMID 36185243, 2022). "The expression of CYBRD1, LRP2, TFRC, SLC22A17, HEPH, SLC39A14, and PCBP2 involved in iron import was associated with poor OS of ovarian cancer, whereas the expression of LCN2, CP, SLC46A1, STEAP3, and LTF in this process was associated with improved OS in ovarian cancer." (PMID 38186569, 2023). "But understanding the mechanistic involvement of TFRC and PDLIM3 in drug resistance would be a valuable insight into predicting chemotherapy efficacy and guiding therapeutic strategies for ovarian cancer patients." (PMID 40697100, 2025). "This is the case with ovarian cancer tumor-initiating cells, intrinsically marked by decreased expression of ferroportin (FPN), an iron efflux pump, and increased expression of transferrin receptor (TfR1), an iron importer." (PMID 36835045, 2023). "This suggests that TFRC-mediated iron uptake primarily affects the malignant progression of ovarian cancer by promoting cell proliferation rather than inhibiting apoptosis." (PMID 38740757, 2024). "Five genes are amplified in > 5% of the corresponding TCGA cohorts: E2F3 (cytoband 6p22.3, 15.7% of bladder cancer), TFRC (3q29, 13.0% of head and neck cancers), MFSD3 (8q24.3, 7.9% of head and neck cancers, FKBP4 (12p13.33, 6.8% of ovarian carcinoma) and FBXL20 (17q12, 6.4% of gastric cancer)." (PMID 34313788, 2021).
lymphoma (28 papers, 1996 to 2025). A malignant (clonal) proliferation of B- lymphocytes or T- lymphocytes which involves the lymph nodes, bone marrow and/or extranodal sites. "A recent study used erastin to induce lymphoma cell ferroptosis and found that TFRC staining was localized to the plasma membrane and to a perinuclear region associated with the Golgi and the endosomal recycling compartment (ERC)." (PMID 35821227, 2022). "In another study, a mouse monoclonal was shown to induce apoptosis only in T lymphocytes of acute T-cell leukemia patients, but not in PBMC from healthy donors and in line with this finding, an anti-TfRC IgA showed clinical responses in lymphoma patients." (PMID 18231595, 2008). "Interestingly, the lymphoma-associated MYC oncogene is involved in iron metabolism and can increase intracellular LIP by activating transferrin receptor 1 (TFR1)." (PMID 38007476, 2023). "With the aim of selectively increasing 67Ga uptake, we studied whether the transferrin receptor (TfR) expression could be modulated in the U937 and U715 lymphoma cell lines by cytostatic drugs inducing cell cycle phase accumulation." (PMID 8761380, 1996). "Additionally, TFRC enhances cellular production of ROS and mitochondrial respiration, leading to the development of pancreatic ductal adenocarcinoma and induction of c-Myc lymphoma-mediated tumorigenesis." (PMID 37940859, 2023). "It has been shown that upregulation of MYC leads to increased surface expression of transferrin receptor (TfR), hence 89Zr-transferrin was developed as a potential probe for MYC status and tumor burden in several cancer models, such as prostate cancer and lymphoma." (PMID 33986665, 2021).
diabetes (27 papers, 2012 to 2025). "The ratio of serum transferrin receptor (sTfR) to SF (sTfR/SF ratio) was inversely associated with diabetes in case-control studies and in a case-cohort study." (PMID 28331855, 2017). "Furthermore, this oxidative milieu synergized with diabetes-associated iron dyshomeostasis, which was characterized by upregulated transferrin receptor expression and suppressed FPN1 levels." (PMID 40276370, 2025). "Increased Fe2+ concentration and expression of TFRC and decreased FTH are found in the hippocampal neurons in high-fat diet (HFD)/STZ-induced type 2 diabetic mice, and are associated with declined expressions of GPX4 and SLC7A11." (PMID 40871742, 2025). "Several studies suggest that iron metabolism indicators (eg, ferritin, hepcidin, soluble transferrin receptor [sTfR]) have roles in the development of diabetes." (PMID 38840960, 2024). "According to the GSEA-KEGG results, TFRC was mainly enriched in cell cycle, DNA duplication, neural active ligand‒receptor interaction, and axon pathways leading to mature diabetes in young individuals." (PMID 36532744, 2022). "For example, transferrin receptor (TFRC), hemochromatosis (HFE), and heme oxygenase 1 (HMOX1) are associated with an increased risk of diabetes, while transmembrane protease, serine (TMPRS), and mothers against decapentaplegic homolog 7 (SMAD7) are associated with a decreased risk." (PMID 40871742, 2025). "Upstream regulator analysis suggested COMMD1, HIF1A, EGLN, PIK3R1 and MTORC1 as major upstream regulators for the phase shifts, while HSP90B1, YWHAZ, CNGA3, COL2A1 and TFRC were identified as the major upstream regulators for the amplitude changes observed in the diabetic retina." (PMID 38039846, 2024). "Hepcidin-25 levels were independently and positively associated with ferritin (p<0.001), hsCRP (p<0.001) and the presence of diabetes (p = 0.02) and inversely with the estimated glomerular filtration rate (p = 0.01), absolute reticulocyte count (p = 0.02) and soluble transferrin receptor (p<0.001)." (PMID 22808058, 2012). "High ferritin levels are associated with higher risk of type 2 diabetes independently of established diabetes risk factors and a range of diabetes biomarkers whereas soluble transferrin receptor concentrations are not related to risk." (PMID 22752055, 2012). "Our study found that the expression level of TFRC in blood samples of DD patients was significantly higher than that of T2DM patients, indicating that DD patients had more severe insulin resistance and symptoms of diabetes than T2DM." (PMID 31341180, 2019).
viral infection (27 papers, 2010 to 2026). "Other novel therapies such as antibody blockade of NW arenavirus receptor human transferrin receptor 1 (hTFR1), which is the receptor used by all the pathogenic clade B NW arenaviruses, has recently shown promise in preventing viral infection with the potential for cross protection." (PMID 37682988, 2023). "Recombinant feline transferrin receptor 1 (fTfR1) and the giant panda ortholog (gpTfR1) were expressed in non-susceptible HEK293T and HeLa cells, while viral infection levels were measured to determine the effect of gpTfR1 on pFPV-sc replication." (PMID 40711262, 2025). "However, FPV may also enter cells through alternative internalisation mechanisms, as deletions or mutations in the internalisation motif of the transferrin receptor, while decreasing FPV cellular uptake, did not completely arrest viral infection." (PMID 33096814, 2020).
colon carcinoma (26 papers, 2006 to 2026). "Our data indicates that the stimulatory effects on apoptosis, rather than the blockage of ferroptosis‐related inflammation, contributes to decreased colon tumor growth after TFRC loss." (PMID 36703617, 2023). "Several studies have suggested that TFRC is abundantly expressed in liver, breast, lung and colon cancer cells and that this increased expression may be associated with poor prognosis in different types of cancer." (PMID 40510157, 2025). "In studies of pancreatic and colon cancer cells, TFRC has been shown to modulate the MAPK signaling pathway, contributing to increased cell viability and resistance to apoptosis." (PMID 40303995, 2025). "The transferrin receptor (TfR) is overexpressed in a variety of cancers, including breast, liver, brain, lung, ovarian, thyroid, esophageal, and colon cancers." (PMID 39861688, 2024). "TFRC is induced by adenomatous polyposis coli (APC) gene loss-driven β-catenin activation in CRC, iron chelation, and TFRC disruption increase DNA replication stress, DNA damage response, apoptosis, and reduce colon tumor growth." (PMID 36910614, 2023). "By qPCR, immunoblotting, and immunofluorescence staining, we confirmed that TFRC expression was relatively low in normal colons, but greatly increased in colon tumors." (PMID 36703617, 2023). "POLD1 knockdown, iron chelation, and TFRC disruption increase DNA replication stress, DNA damage response, apoptosis, and reduce colon tumor growth." (PMID 36703617, 2023). "In colon tumors, TFRC was expressed both in the cytoplasm and basolateral membrane of epithelial cells." (PMID 36703617, 2023). "Mechanistic study revealed that TFRC‐mediated iron uptake in colon tumors is required to maintain the activity of the metal‐dependent TNKS." (PMID 36703617, 2023). "Transferrin receptor (TFRC)‐mediated iron uptake in colon tumors is essential to maintain the activity of tankyrase (TNKS)." (PMID 36703617, 2023). "Gene expression of iron importers, divalent metal transporter 1 and transferrin receptor 1, increased and iron exporter, ferroportin, decreased in colonic tumors suggesting increased iron uptake." (PMID 24223168, 2013). "In this study, we found fragmentation of Golgi structure, suppression of transferrin receptor expression, production of oxidants, and DNA fragmentation in human colon cancer HT29 cells after treatment with geoditin A for 24 h." (PMID 20161972, 2010). "In the large intestine HT-29 cell lines, EGCG increased the activity of TfR (transferrin receptor), which is a carrier protein for transferrin, and inhibited the activity of the ferritin-H protein through iron chelating activity in HT-29 colon cancer cells." (PMID 37241819, 2023). "However, we found that TFRC expression was paradoxically induced in iron‐enriched colon tumors and further potentiated by a high‐iron diet." (PMID 36703617, 2023). "Surprisingly, the induction of TFRC in colon tumors was further potentiated by the high iron diet." (PMID 36703617, 2023). "This study describes a complete strategy forthe development of a gastric cancer model in mouse and also confirmedthe enhanced transferrin receptor expression on gastric cancer tissue.Transferrin receptors can be used as a site for targeted drug deliveryto gastric and colon cancer." (PMID 34778662, 2021). "Immunoblotting analysis showed that TFRC and FTH1 protein expression were reduced in colon tumors from CDX2ERT2TfrcF/FApcF/+ mice." (PMID 36703617, 2023). "High expression of TFRC promotes DSS-induced colonic epithelial cell death by activating the IL-6/IL-11-Stat3 pathway, which leads to mucosal injury and the occurrence of colon cancer." (PMID 37940859, 2023). "qPCR analysis demonstrated that TFRC was significantly increased in the colon tumors compared to normal colons from CDX2ERT2 Tfrc+/+ApcF/+ mice, whereas TFRC disruption greatly reduced the increased TFRC in colon tumors from CDX2ERT2 TfrcF/FApcF/+ mice." (PMID 36703617, 2023).
thalassemia (25 papers, 2013 to 2025). An inherited blood disorder characterized by a decreased synthesis of one of the polypeptide chains that form hemoglobin. "This latter study also found that heterozygous and homozygous Hb E, with or without α-thalassaemia trait, increased plasma ferritin and soluble transferrin receptor (sTfR) concentrations likely due to ineffective erythropoiesis and/or increased Fe absorption." (PMID 31303184, 2019).